SIRT3 (sirtuin 3)
Diseases named in the same sentence as SIRT3 in open-access papers (continued):
Sharing a sentence is not in itself a finding about the gene and the disease.
endometriosis (2 papers, 2023 to 2025). The growth of functional endometrial tissue in anatomic sites outside the uterine body. "Our findings suggest that SIRT3 may be associated with the severity of endometriosis." (PMID 41009667, 2025). "A notable outcome of our study was the identification of elevated SIRT3 levels in PBMCs in patients with advanced endometriosis who had undergone surgical intervention." (PMID 41009667, 2025). "This longitudinal study compares oxidative stress markers and SIRT3 levels in patients with different endometriosis types." (PMID 41009667, 2025). "The finding that SIRT3 levels are elevated in patients with a history of previous endometriosis surgery raises interesting questions about the long-term impact of surgical interventions on oxidative stress." (PMID 41009667, 2025). "The most important finding of our study was the significant elevation of SIRT3 levels in PBMCs in patients with DE compared to those with OMA (referring to endometriosis phenotype limited to the ovary)." (PMID 41009667, 2025). "Oxidative stress plays a key role in endometriosis, with sirtuins, especially SIRT3, emerging as important regulators." (PMID 41009667, 2025). "The study successfully identified an elevation of SIRT3 in PBMCs in patients with advanced endometriosis who had undergone surgical intervention." (PMID 41009667, 2025). "Further research is needed to understand the role of SIRT3 in the progression of endometriosis and its potential as a biomarker for disease severity." (PMID 41009667, 2025). "The conclusion of the study is that Sirtuin 3 (SIRT3) levels are significantly elevated in patients with more severe phenotype of endometriosis." (PMID 41009667, 2025). "Furthermore, dysregulated SIRT3 activity would facilitate the invasive and fibrotic features of deep endometriosis." (PMID 41009667, 2025). "The oxidative stress regulators of the molecular pathways involved in the production of free radicals and antioxidants, showed similar results between the two groups, except for SIRT3 levels in the blood leukocyte population, which were statistically higher in patients with deep endometriosis." (PMID 41009667, 2025). "The predominant mitochondrial localization of SIRT3 makes it particularly relevant for investigating mitochondrial function and oxidative stress response, both of which are crucial aspects in the pathophysiology of endometriosis." (PMID 41009667, 2025). "The findings suggest SIRT3 as a potential therapeutic target in endometriosis management." (PMID 41009667, 2025). "In addition, elevated SIRT3 levels in the blood cells of patients with deep endometriosis may reflect important alterations in cellular metabolism and mitochondrial homeostasis." (PMID 41009667, 2025). "The increased expression of SIRT3 in PBMCs of DE patients may suggest that this form of endometriosis may have a more systemic impact than previously thought which aligns with the notion that DE is the most severe form of endometriosis leading to more pronounced symptoms." (PMID 41009667, 2025). "HDAC1, HDAC2, HDAC3, Sirtuin 1, and Sirtuin 3, are the five most studied HDAC enzymes which seem to, at least partly, influence the pathophysiology of endometriosis." (PMID 37174627, 2023). "Moreover, the correlation observed between elevated SIRT3 and SOD2 levels further supports the idea of a coordinated antioxidant response in severe endometriosis, potentially mitigating oxidative stress despite the disease’s severity." (PMID 41009667, 2025). "The results demonstrated that patients with a history of prior surgery for endometriosis exhibited significantly higher SIRT3 levels in PBMCs, a trend not observed in relation to antioxidant supplementation or prior hormonal therapy." (PMID 41009667, 2025). "Together, these findings indicate that SIRT3 may help reduce the negative effects of oxidative stress in endometriosis and could be a new approach to improve oocyte quality and IVF outcomes." (PMID 41009667, 2025).
energy metabolic disorders (2 papers, 2019 to 2024). "Energy metabolism disorders and neuroinflammation caused by SIRT3 deficiency in metabolic diseases can cause cognitive dysfunction." (PMID 37659035, 2024). "Furthermore, ginsenoside Rg1 maybe a molecule that can be used as an agonist of Sirt3, targeting the energy metabolic disorders and oxidative stress of mitochondria for prevention of I/S-induced neurocognitive disorders." (PMID 31652451, 2019).
gastric tumor (2 papers, 2015 to 2019). "In consistence, a cluster of glycolysis-associated genes was upregulated in the SIRT3-overexpressing gastric tumor cells." (PMID 26121691, 2015). "Overexpression of SIRT3 promoted cell proliferation and enhanced ATP generation, glucose uptake, glycogen formation, MnSOD activity and lactate production, which were inhibited by SIRT3 knockdown, indicating that SIRT3 plays a role in reprogramming the bioenergetics in gastric tumor cells." (PMID 26121691, 2015).
Headache (2 papers, 2023 to 2025). Cephalgia, or pain sensed in various parts of the head, not confined to the area of distribution of any nerve. "Our results have identified that SS-31 has the potential to be an effective drug candidate for headache treatment, and Sirt3/Pgc-1α positive feedback loop may represents an underlying target for therapeutic intervention of headache." (PMID 37271805, 2023). "The roles of the Sirt3/Pgc‐1α positive feedback loop in mitochondrial function and headache pathogenesis were examined." (PMID 40542608, 2025). "Here we used a mouse model induced by repeated dural infusion of inflammatory soup (IS), and examined roles of Sirt3/Pgc-1α positive feedback loop in headache pathogenesis and mitochondrial function." (PMID 37271805, 2023). "We concluded that SS-31 alleviated nociceptive responses and restored mitochondrial function in IS-induced headache via Sirt3/Pgc-1α positive feedback loop." (PMID 37271805, 2023). "Based on the proven fact that Sirt3 and Pgc-1α take part in maintaining mitochondrial homeostasis, we investigated whether Sirt3 and Pgc-1α play roles in the effects of SS-31 on IS-induced headache." (PMID 37271805, 2023). "Thus, we proposed the following hypotheses according to above evidence: the mitochondria-targeted antioxidant peptide SS-31 alleviated nociceptive responses and restored mitochondrial function in a headache mouse model via mitochondrial homeostasis regulated by Sirt3/Pgc-1α positive feedback loop." (PMID 37271805, 2023). "Our findings showed that the inhibitors of Sirt3 and Pgc-1α increased nociceptive responses, injured mitochondrial function and suppressed mitochondrial biogenesis, indicating that Sirt3 and Pgc-1α may represent potential targets for therapeutic intervention of headache." (PMID 37271805, 2023).
Hypoglycemia (2 papers, 2021 to 2024). A decreased concentration of glucose in the blood. "Sirt3−/− mutant studies have shown decreased fatty acid oxidation, low ATP production, and the animals have developed fatty liver and shown defects in thermogenesis and hypoglycemia during cold tests." (PMID 34769236, 2021).
IgA nephropathy (2 papers, 2020 to 2022). "We also examined intra-renal expression levels of Sirt1, Sirt3, Sirt6, and Nmnat1 in specimens from patients with IgA nephropathy." (PMID 35962139, 2022). "Intra-renal expression levels of Sirt1, Sirt3, Sirt6, and Nmnat1 were evaluated in specimens from 27 patients who were histologically diagnosed with FSGS and IgA nephropathy." (PMID 35962139, 2022).
insulinoma (2 papers, 2019 to 2020). "Particularly, SIRT3 overexpression in murine insulinoma NIT1 cells significantly blunted palmitate-induced apoptosis, as reported by the reduced levels of caspase 3 activity compared to control cells." (PMID 31557786, 2019). "Both SIRT3 mRNA and protein expression was significantly lower in the rat insulinoma cell line (INS-1) after proinflammatory stimuli such as TNFα and IL-1β, markers that are significantly increased in diabetic individuals." (PMID 31557786, 2019). "Furthermore, SIRT3 knockdown in the primary culture of islets isolated from SIRT3 KO mice and pancreatic β cell line (MIN6) derived from a mouse insulinoma both revealed a decline of the MnSOD activity and impairment of glucose-stimulated insulin secretion and ATP production." (PMID 32722262, 2020).
kidney tumor (2 papers, 2020 to 2022). "Recent studies have found a relationship between SirT3 overexpression and mitochondrial biogenesis activation in kidney tumor cells and osteoblasts." (PMID 32721927, 2020).
knee osteoarthritis (2 papers, 2023 to 2024). "In knee osteoarthritis, SIRT3 regulates Atrogin-1 and MuRF-1 levels by decreasing SOD2 acetylation and reducing reactive oxygen species (ROS) levels." (PMID 39519152, 2024). "Based on another study, the SIRT3-induced AMPK pharmacologic activation represses the oxidative stress while enhancing the mtDNA integrity to limit the development and progression of aging-triggered knee osteoarthritis (OA) in mice." (PMID 36846717, 2023).
MELAS (2 papers, 2017 to 2020). "We further compared the protein expression of Sirtuin-3 (Sirt3) between the MELAS and control cells and found that the Sirt3 levels were significantly increased in the MELAS cells (1.33 ± 0.05 of control)." (PMID 29088732, 2017). "While one study showed comparable expression of Nrf1 and Tfam and upregulation of PGC-1α and SIRT3 in MELAS patients compared to controls, another one reported similar expression rates of PGC-1α and upregulation of Tfam in patients compared with that of controls." (PMID 32722320, 2020).
nephritis (2 papers, 2024 to 2025). Inflammation of renal tissue. "On the basis of previous in vitro and in vivo studies, we know that SIRT3 is somehow involved in the protective effects of the receptor agonist DEX against the damage from nephritis caused by I/R injury, prompting us to investigate the nature of this involvement more clearly." (PMID 38270316, 2024). "DEX protects against nephritis by upregulating SIRT3 expression, which mitigates inflammation, oxidative stress, and apoptosis in renal cells both in vivo and in vitro." (PMID 40635757, 2025). "In this study, the role of SIRT3 in DEX‐mediated amelioration of inflammation and oxidative stress in nephritis as well as the possible underlying mechanism were explored in vivo and in vitro." (PMID 38270316, 2024). "Our results suggest that DEX exhibits renoprotective activity during nephritis progression, protecting renal cells against inflammatory injury by promoting SIRT3 expression." (PMID 38270316, 2024). "Dexmedetomidine (DEX) prevents nephritis by upregulating although sirtuin 3 (SIRT3) expression." (PMID 38270316, 2024). "SIRT3 knockdown inhibited the renoprotective effects of DEX against nephritis." (PMID 38270316, 2024). "Although sirtuin 3 (SIRT3) is known to be involved in dexmedetomidine (DEX)‐mediated alleviation of renal ischemia and reperfusion injury, the influence of the association between DEX and SIRT3 on nephritis development remains unclear." (PMID 38270316, 2024). "Therefore, we concluded that DEX prevents nephritis by upregulating SIRT3 expression." (PMID 38270316, 2024). "However, whether and how SIRT3 is involved in nephritis‐induced kidney injury remains unknown." (PMID 38270316, 2024). "Therefore, in the present study, we established both animal and cell‐based models of nephritis to examine whether DEX could alleviate renal injury in LN and to elucidate its role in the activation of SIRT3." (PMID 38270316, 2024).
neuropathies (2 papers, 2022 to 2024). "Given our observation of mitochondrial alterations in PDN rats and the lack of correlation between SIRT4 and SIRT5 with DRG or neuropathy, we have chosen to focus our investigation on SIRT3." (PMID 38572816, 2024). "Thus, SIRT3 is essential for honokiol’s activity in the ENS and could be a potential therapeutic target for neuropathies in the ENS." (PMID 36543902, 2022).
nonalcoholic steatohepatitis (2 papers, 2021 to 2022). "For example, salvianolic acid B could reduce oxidative stress response by regulating Sirt3/FoxO1 signaling pathway and play a role in the treatment of nonalcoholic steatohepatitis." (PMID 35959265, 2022).
preeclampsia (2 papers, 2024 to 2025). Preeclampsia is a hypertensive disorder of pregnancy that is characterized by new-onset hypertension with proteinuria presenting after 20 weeks of gestation, and depending on mild or severe forms may initially present with severe headache, visual disturbances, and hyperreflexia. "Notably, SIRT3 deficiency leads to resistance to autophagy-dependent ferroptosis and is implicated in the development of preeclampsia by promoting necroptosis, highlighting the importance of SIRT3 as a potential target for RCD regulation." (PMID 38409106, 2024). "The aberrant expression of SIRT3 in placentas affected by pregnancy complications such as preeclampsia exerts well-documented detrimental effects." (PMID 40881171, 2025). "Therefore, SIRT3 may serve as a potential target for both the diagnosis and treatment of preeclampsia." (PMID 40881171, 2025).
pulmonary disease (2 papers, 2022 to 2023). "We studied the association between two SIRT3 gene functionalpolymorphisms (rs3782116 and rs536715) and сhronicobstructive pulmonary disease." (PMID 37867611, 2023).
renal carcinoma (2 papers, 2020). A carcinoma arising from the epithelium of the renal parenchyma or the renal pelvis. "In renal cancer, SIRT3 was reported to be down-regulated in KIRC tissues and predicted a favorable survival of KIRC patients." (PMID 32158696, 2020). "In renal cancer cells where pyruvate dependent mitochondrial usage is compromised, SIRT3 supports tumor growth by promoting glutamine derived mitochondrial respiration." (PMID 33273545, 2020).
renal cell carcinoma (2 papers, 2022 to 2023). "The current study revealed a significant association between ARK5 and SIRT3 expression in renal cell carcinoma cases collectively and clear cell type specifically and shorter patients’ survival but none of them was an independent variable." (PMID 37996927, 2023). "Kaplan Meier univariate survival analysis of all renal cell carcinoma cases was done using the Log Rank test, it revealed significant associations between short survival duration and both nucleocytoplasmic expression of ARK5 and positive SIRT3 expression (P = 0.014 and 0.035)." (PMID 37996927, 2023).
rheumatoid arthritis (2 papers, 2021 to 2024). A chronic, systemic autoimmune disorder characterized by inflammation in the synovial membranes and articular surfaces. "In addition, in patients with rheumatoid arthritis, SIRT-3 mRNA expression levels were found to be increased as a compensatory response to oxidative stress and were significantly higher in patients receiving corticosteroid therapy, suggesting that this therapy may influence the levels detected." (PMID 38678247, 2024).
scleroderma (2 papers, 2016 to 2023). Scleroderma is a rare autoimmune connective tissue disorder characterized by abnormal hardening of the skin and, sometimes, other organs. "Taken together, these results indicate that SIRT3 levels and activity are impaired in fibrotic lesions and explanted skin fibroblasts in SSc, as well as in a mouse model of scleroderma." (PMID 27732568, 2016). "We next examined Sirt3 expression in a murine model of scleroderma induced by s.c. bleomycin." (PMID 27732568, 2016).
seminoma (2 papers, 2022 to 2024). A radiosensitive malignant germ cell tumor found in the testis (especially undescended), and extragonadal sites (anterior mediastinum and pineal gland). "Specifically, E2 treatment has been demonstrated to elevate Sirt3 levels in both seminoma cells and human umbilical vein endothelial cells (HUVECs)." (PMID 39272992, 2024). "Two previous reports demonstrated that E2 upregulates Sirt3 in seminoma cells and HUVECs." (PMID 39272992, 2024). "A working model was also further proposed for the protecting action of ERβ against seminoma, in which ERβ regulated the gene expression of SIRT3, a major mitochondria nicotine adenine dinucleotide (NAD)+-dependent deacetylase, and resulted in ROS level reduction." (PMID 36548865, 2022).
skin aging (2 papers, 2025). The gradual irreversible changes in structure of skin that occur as a result of the passage of time.. "SIRT3, an NAD+-dependent deacetylase, has been reported to regulate mitochondrial function and autophagy, making it a promising therapeutic target for skin aging." (PMID 41008947, 2025).
spinal cord ischemia (2 papers, 2022 to 2023). Reduced blood flow to the spinal cord which is supplied by the anterior spinal artery and the paired posterior spinal arteries. "RIPC enhances spinal cord ischemia tolerance in a SIRT3-dependent manner, and its induced elevated SIRT3 levels are mediated by the NMDAR-AMPK-PGC-1α signaling pathway." (PMID 36927808, 2023). "In a spinal cord ischemia model, MMP loss and neuronal apoptosis were protected by ZL006 by stimulating SOD2 deacetylation and mitochondrial enzyme activities in a SIRT3-dependent manner." (PMID 35372451, 2022). "Here, we hypothesized that RIPC enhances neuronal antioxidant signaling and improves spinal cord ischemia tolerance by increasing SIRT3 expression." (PMID 36927808, 2023). "However, whether SIRT3 is involved in RIPC-mediated enhancement of spinal cord ischemia tolerance has not been reported." (PMID 36927808, 2023).
Splenomegaly (2 papers, 2019 to 2023). Abnormal increased size of the spleen. "The splenomegaly of mice from the Sirt3-/- group was more significant." (PMID 37275851, 2023).
temporal lobe epilepsy (2 papers, 2017). A localization-related (focal) form of epilepsy characterized by recurrent seizures that arise from foci within the temporal lobe, most commonly from its mesial aspect. "SIRT3 can maintain the balance of protein acetylation in mitochondrial neurons, and its deficiency or reduction in mouse models of temporal lobe epilepsy also results in hyperacetylation of CypD." (PMID 28236057, 2017).
thrombosis (2 papers, 2017 to 2018). "Neutrophil count was elevated after DVT formation in both genotypes, and significantly higher numbers were observed in Sirt3-/- compared with WT mice, indicating that the systemic response to thrombosis was enhanced in Sirt3-/- mice." (PMID 29236713, 2017). "Sirt3-/- and WT mice were subjected to inferior vena cava (IVC) stenosis, which recapitulates key features of deep vein thrombosis (DVT) progression on humans." (PMID 29236713, 2017).
acute liver failure (1 paper, 2022). Rapid deterioration of liver function causing encephalopathy and coagulopathy. "The purpose of the study was to explore the effects of SIRT3 inhibitor 3-TYP on acute liver failure (ALF) in mice and its underlying mechanism." (PMID 35923224, 2022).
acute peritonitis (1 paper, 2017). "SIRT3 deficiency did not impact on the development of sub-acute pneumoniae and acute peritonitis, going well along with normal in vitro responses to bacterial stimulation of immune cells." (PMID 28634345, 2017).
adenovirus infection (1 paper, 2015). "When SIRT3 was silenced, the inhibitory effect of MIAM on Bel-7402/5FU was lowered, showing the characteristic of resistance against MIAM, whereas Bel-7402/5FU cells with high expression of SIRT3 by SIRT3 adenovirus infection demonstrated the high sensitivity to MIAM." (PMID 25961022, 2015).
age-related macular degeneration (1 paper, 2017). Age-related loss of vision in the central portion of the retina (macula), secondary to retinal degeneration. "Our findings help clarify the important role of SIRT3 in retinal neurodegeneration and offer the possibility of modulating SIRT3 activity as a novel therapeutic avenue for oxidative stress-induced retinal diseases such as age-related macular degeneration." (PMID 29214052, 2017).